MMP9 (matrix metallopeptidase 9)
Diseases named in the same sentence as MMP9 in open-access papers (continued):
Sharing a sentence is not in itself a finding about the gene and the disease.
nasal polyps (20 papers, 2010 to 2024). "MMP-9, which mainly degrades gelatin, aggrecan, and elastin, was considered to be associated with nasal polyp formation and TIMP-1 regulated MMP-9 activity." (PMID 33477617, 2021). "The most significant result was from the promoter polymorphism of the MMP-9 gene (rs3918242, i.e. -1562 C/T), which indicates that the rare T allele would significantly increase the risk for nasal polyposis." (PMID 20529372, 2010). "In conclusion, our study provides novel evidence to support genetic polymorphisms in the MMP9 gene can influence the risk for chronic rhinosinusitis with nasal polyposis." (PMID 20529372, 2010). "The upregulation of MMP9 expression by EOS has also been demonstrated in nasal polyposis and this may reveal an association between MMP9 and EOS." (PMID 25187823, 2014). "We conducted a case-control study to systematically investigate the role of MMP-9 tagging single nucleotide polymorphisms (tSNPs) and a promoter functional polymorphism in the development of chronic rhinosinusitis with nasal polyposis in a Chinese population residing in Taiwan." (PMID 20529372, 2010). "Furthermore, the T allele of the functional promoter SNP rs3918242 that has been shown to increase MMP-9 expression is also a risk allele for chronic rhinosinusitis with nasal polyposis." (PMID 20529372, 2010). "We concluded that MMP-9 gene polymorphisms may influence susceptibility to the development of chronic rhinosinusitis with nasal polyposis in Chinese population." (PMID 20529372, 2010). "We hypothesized that genetic variants of the MMP-9 gene are associated with cases of chronic rhinosinusitis with nasal polyposis." (PMID 20529372, 2010). "Previous studies provided evidence for higher levels of MMP‐1, MMP‐2, MMP‐3, MMP‐7, MMP‐8, and MMP‐9 in nasal polyps." (PMID 34504680, 2021). "In conclusion, we demonstrated prominent expression of IL‐19 in nasal polyps of patients with CRSwNP, along with increased expression of tissue remodeling factor MMP‐9." (PMID 33900049, 2021). "Tetracycline and macrocyclic lipid drugs (MMP inhibitors), which can reduce the formation of nasal polyps through down-regulation of MMP-9 levels." (PMID 30283454, 2018). "The MMP-9 level was elevated in nasal polyps and the TIMP-1 level was elevated in chronic rhinosinusitis." (PMID 29076987, 2017). "Although fungi did not influence the production of MMP-9 protein, melittin and apamin tended to inhibit the production of MMP-9 from nasal polyp fibroblasts." (PMID 29076987, 2017). "We systematically investigated four SNPs at MMP-9 in relation to chronic rhinosinusitis with nasal polyposis in a Chinese population residing in Taiwan." (PMID 20529372, 2010). "They hypothesized based on their study findings that when stimulated by IL-5, EDN degranulation promotes MMP-9 secretion from the nasal epithelium, possibly accounting for nasal tissue remodelling and subsequently nasal polyposis." (PMID 36832203, 2023). "Previous studies demonstrated that TGF-β1, MMP2, MMP7, and MMP9 could induce EMT in nasal polyps and can be synthesized and secreted by macrophages." (PMID 35990621, 2022). "Doxycycline could have the potential to reduce nasal polyp volume by decreasing MMP-9 levels and reducing MUC5AC levels." (PMID 33477617, 2021). "However, another study revealed that the increased levels of MMP-2 in nasal polyps elevated MMP-9 expression in CRSsNP, and decreased levels of TIMP-1 in both CRSsNP and CRSwNP were comparable to those in the controls." (PMID 33477617, 2021). "Furthermore, MMP-9 expression is elevated and closely correlated with the recurrence and severity of chronic sinusitis and nasal polyps, particularly in naso-sinal bone lesions, in line with the preponderance of NET-induced MMP-9 in H&N GPA patients." (PMID 31798577, 2019). "Other studies found an association of nasal polyps with MMP-9 polymorphisms, but not with MMP-2 ones." (PMID 28400178, 2017).
nasal polyps (continued). "Findings of increased concentrations of MMP-9, but not of TIMP-1, in nasal polyps suggest that the MMP-9/TIMP-1 imbalance is associated with ECM degradation in CRSwNP." (PMID 25379119, 2014). "Upregulation of MMP-9 in the nasal polyposis may damage the collagen of basement membrane of epithelia and blood vessels, causing increases in permeability and edema in the stroma." (PMID 20529372, 2010). "Furthermore, vitamin D derivatives could significantly inhibit TNF-α-induced matrix metalloproteinase-2 (MMP-2) and matrix metalloproteinase-9 (MMP-9) secretion in fibroblasts involved in nasal polyp genesis." (PMID 34440059, 2021). "In an experimental study using organ culture of nasal polyps, S. aureus infection promoted the release of MMP-2, MMP-9, TIMP-1, and Th2 cytokines, including IL-5, IL-13, and eotaxin." (PMID 33477617, 2021). "Therefore MMP-9 may play a role in the pathogenesis or recurrence of the nasal polyposis." (PMID 20529372, 2010). "Therefore, the current data showed that MMP-9 polymorphisms might influence susceptibility to the development of chronic rhinosinusitis with nasal polyposis but might not increase the risk for recurrence." (PMID 20529372, 2010). "Two studies found an association of MMP-9 and MMP-2 polymorphisms and chronic rhinosinusitis with nasal polyps, but not in patients with recurrent nasal polyps." (PMID 28400178, 2017). "Elevated levels of MMP-9 protein and MMP-9 mRNA were found in the cases of nasal polyposis." (PMID 20529372, 2010). "However, expressions of MMP-2 and MMP-9 are not sensitive to LPS exposure in nasal polyp fibroblasts." (PMID 25390332, 2014). "Variations in goblet cell hyperplasia, collagen fibre density, and the expression of matrix metalloproteinase-9 (MMP-9) and transforming growth factor-beta 1 (TGF-β1) have also been noted between CRS cases with and without nasal polyps in the context of AR." (PMID 39131035, 2024).
Parkinson disease (20 papers, 2013 to 2025). A progressive degenerative disorder of the central nervous system characterized by loss of dopamine producing neurons in the substantia nigra and the presence of Lewy bodies in the substantia nigra and locus coeruleus. "Other notable observations include the downregulated levels of OSM, MNDA, AZU1 and MMP9, which are well-known neuroinflammatory markers, proven in several Parkinson’s disease models." (PMID 39816194, 2025). "Parkinson's disease, which ordinarily begins in late life, has been reported to be associated with aberrant expression of MMP-3 and MMP-9." (PMID 35444067, 2022). "Parkinson's disease has been associated with aberrant expression of MMP-3 and MMP-9." (PMID 35444067, 2022).
retinoblastoma (20 papers, 2013 to 2025). A malignant tumor that originates in the nuclear layer of the retina. "MMP2 and MMP9 have been implicated in promoting cell migration, viability, and the secretion of angiogenic factors in retinoblastoma cells." (PMID 40332443, 2025). "Eriodictyol, a natural dihydroflavonoid, caused significant inhibition of migration and invasion of retinoblastoma cells; this resulted from downregulation of MMP-2 and MMP-9 protein expression and blockage of the Akt and PI3K signaling pathways." (PMID 35457074, 2022). "Higher MMP-9 expression is associated with a more advanced stage of disease; MMP-2 is believed to regulate the differentiation of retinoblastoma cells via the activation of ERK1/2 pathway." (PMID 35457074, 2022). "In hypoxic conditions, hypoxia promotes the invasion of retinoblastoma HXO-RB44 cells by activating the HIF-1α/MMP9 signaling pathway." (PMID 36118887, 2022). "In addition, higher levels of MMP-2 and MMP-9 in retinoblastoma cells are associated with an elevated risk of optic nerve invasion by cancer, suggesting that they may be responsible for increased malignancy of retinoblastoma, and their presence indicates the need for more aggressive therapy." (PMID 35457074, 2022). "The levels of MMP-1, MMP-2, and MMP-9 have also been found to have a significant positive correlation with the intensity of retinoblastoma invasion and the occurrence of metastases." (PMID 35457074, 2022). "High expression of cyclin-D2 and MMP-9 increases the cell division rate and progression of retinoblastoma." (PMID 34646884, 2021). "In this meta-analysis, we assessed the clinicopathological significance of MMPs and VEGF in retinoblastoma and detected a potential relationship between MMP-9 and VEGF expression." (PMID 31311559, 2019). "After comprehensive study, they found that MMP-2 and -9 are involved in stimulating cell migration and contributing to cell viability whereas MMP-9 played an additional role in Angiopoietin-2 production thus enhancing angiogenesis in retinoblastoma cells." (PMID 29233192, 2017). "Collectively, our data indicates MMP-2 and MMP-9 drive metastatic pathways, including migration, viability and secretion of angiogenic factors in Rb cells." (PMID 28633655, 2017). "Our work focuses on MMP-2 and MMP-9 activity in Rb, the most common intraocular malignancy in children." (PMID 28633655, 2017). "Our results demonstrated that STAT3 activation induced up-regulation of BCL2, BCL2L1, BIRC5, and MMP9 genes in retinoblastoma cells." (PMID 25359779, 2014). "For example, MMP9 is up-regulated in the proliferation of retinoblastoma cells and is highly expressed in tumor tissues with optic nerve invasion." (PMID 25359779, 2014). "A notable fact is that MMP9, which demonstrated the most up-regulated mRNA expression, reflected the level of proliferation and invasiveness of retinoblastoma cells." (PMID 25359779, 2014). "In conclusion, SUZ12 siRNA inhibited cell invasion and the expression of VEGF, MMP-2 and MMP-9 in SO-RB50 retinoblastoma cells." (PMID 25295075, 2014). "For example, MMP-9 causes release of vascular endothelial growth factor (VEGF) to promote angiogenesis, and inhibition of MMP-9 decreases both cell migration and angiogenesis in retinoblastoma." (PMID 38659028, 2024). "Interestingly, the selective inhibition of MMP-2 and MMP-9 in retinoblastoma reduces the production of TGF-β1, the key factor for EMT, known to facilitate invasion and metastasis providing an insight into the wider role of MMPs." (PMID 35457074, 2022). "Cyclin-D2 and MMP-9 are two key genes that are regulated by miR-204 in retinoblastoma." (PMID 34646884, 2021). "Furthermore, target genes of STAT3 including BCL2, BCL2L1, BIRC5, and MMP9 are up-regulated in retinoblastoma cells compared to other retinal constituent cells." (PMID 25359779, 2014).
retinoblastoma (continued). "In addition, MMP9 reflected the proliferation of retinoblastoma cells and was highly positive in the tumors with optic nerve invasion, which meant invasiveness of retinoblastoma." (PMID 25359779, 2014). "Our observations align with a previous study on retinoblastoma (RB) that investigated the effects of inactivating MMP‐2 or MMP‐9 in cell migration, invasion, and angiogenesis." (PMID 38064181, 2023). "Based on the recent understanding of the importance of MMP enzymes in retinoblastoma it has also been suggested that differential expression of MMP-9 and MMP-2 could be a significant pathologic factor reflecting the biology of retinoblastoma and may also be used as a monitoring test." (PMID 23129147, 2013). "MMP-1, MMP-2, MMP-9 and VEGF play important roles in the development and progression of retinoblastoma." (PMID 31311559, 2019). "Asymmetry was noted in the analysis of the association between tumor invasion and VEGF expression, as well as the correlation between MMP-9 and VEGF expression in retinoblastoma, indicating possible publication bias." (PMID 31311559, 2019). "The results confirm that MMP-1, MMP-2, MMP-9, and VEGF overexpression is highly related to poor retinoblastoma differentiation and tumor invasion." (PMID 31311559, 2019). "Meanwhile, MMP-9 and VEGF proteins exhibit a system-level coexpression pattern in retinoblastoma, indicating their potentially important biological relationships in tumor development and progression." (PMID 31311559, 2019). "Although we confirmed that MMP-9 and VEGF are coexpressed in retinoblastoma, further exploration is needed to identify the biological role of their interaction." (PMID 31311559, 2019). "Next, we investigated MMP-9 and VEGF coexpression in retinoblastoma tissue, and demonstrated that MMP-9 and VEGF expression are positively correlated (r = 0.61, 95% CI 0.38–0.77, RE model; r = 0.59, 95% CI 0.34–0.77, QE model)." (PMID 31311559, 2019). "Immunohistochemical analysis of primary Rb tumors show that MMP-2 and MMP-9 protein levels are higher in samples that had invaded the optic nerve." (PMID 28633655, 2017). "Using inhibitors of MMP-2 (ARP100) and MMP-9 (AG-L-66085), the migration in metastatic Y79 retinoblastoma cells was inhibited, demonstrating that MMP-2 and MMP-9 could promote Y79 cancer cell migration." (PMID 35326412, 2022). "Seventh, miR-204 downregulation in retinoblastoma suggested that it may act as a tumor suppressor by targeting CCND2 and MMP9." (PMID 32070426, 2020). "We concluded that the overexpression of MMP-1, MMP-2, MMP-9 and VEGF is highly related to poor retinoblastoma differentiation, tumor invasion and advanced clinical stage and, thus, have a role in predicting the prognosis of retinoblastoma patients." (PMID 31311559, 2019). "For example, in retinoblastoma, MMP2 and MMP9 degrade type IV collagen to facilitate invasion." (PMID 31579438, 2019). "For example, MMP-9 and MMP-2 inhibition may reduce VEGF expression and, thus, angiogenesis in retinoblastoma cell lines." (PMID 31311559, 2019). "Although in our study the Y-79 cells did not secrete MMP-9, the expression of this enzyme has been considered to directly contribute to the cellular proliferative process in retinoblastoma." (PMID 23129147, 2013). "Furthermore, MMP-9 and VEGF expression are positively correlated in retinoblastoma tissue, possibly due to the fact that MMP-9 plays a key role in the acquisition of an angiogenic cell phenotype by supporting VEGF secretion while VEGF promotes MMP-9 expression through the activation of ERK pathway." (PMID 35457074, 2022). "Scientists concluded that MMP-2 and MMP-9 drive metastatic pathways, migration, viability, and secretion of angiogenic factors in two cell lines representing the metastatic and nonmetastatic forms of retinoblastoma cells." (PMID 33182665, 2020).
acute kidney injury (19 papers, 2012 to 2025). Sudden and sustained deterioration of the kidney function characterized by decreased glomerular filtration rate, increased serum creatinine or oliguria. "Lack of CD2AP predisposes cells to apoptosis, and therefore reduced level of MMP-9, shown to protect tubular cells against apoptosis in acute kidney injury, could contribute to the susceptibility of CD2AP-deficient podocytes to apoptosis." (PMID 27441654, 2016). "As expected, both jck-MMP9+/+ and jck-MMP9-/- polycystic mice developed renal failure but it was more pronounced in jck-MMP9 deficient mice, as attested by the significantly higher serum creatinine values in 1- and 4- month old jck-MMP9-/- mice compared to their jck-MMP9+/+ littermates." (PMID 38039285, 2023). "During the repair process following acute kidney injury, MMP9 is activated and renal repair is impaired by MMP9 inhibition." (PMID 37791586, 2023). "Both MMP-2 and MMP-9 are increased perivascular in acute kidney injury, and systemic effects were also proved by high levels of MMP-2 and -9 in extrarenal circulation in chronic renal diseases." (PMID 33671770, 2021). "However, at late stages in acute kidney injury (14 days after I/R injury), MMP9 may have a pathogenic role in AKI-CKD transition." (PMID 36077596, 2022). "RT-qPCR validated miRNA and mRNAs included IGFBP2 (respiratory system); MMP9 and PDE4B (nervous system); PPARG (cardiovascular system); AKR1B1, ANXA1, and LNC2/NGAL (acute kidney injury); GFER/ALR (liver); and miR-30c-3p (coagulopathy)." (PMID 34573990, 2021). "It was concluded that biomarkers such as IL-6, IL-8, TNF-α, MMP-9 and NGAL are reliable acute kidney injury indicators." (PMID 34571700, 2021). "However, it was reported that in patients with renal failure, BCAA oral supplementation improves appetite and slows the progression of renal failure, counters oxidative stress in the kidneys, and alleviates diabetic kidney injury via the JNK/TGF-b/MMP-9 pathway." (PMID 37762992, 2023). "Inflammation has been shown to stimulate the expression of MMP-9, and, in the present study, the cases with renal failure also had higher leukocytes counts, and therefore the increase in the presence of the uNGAL MMP9 complex in the renal failure group seems rational." (PMID 25160665, 2014). "Interestingly, a significantly higher frequency of monomer and NGAL/MMP-9 complex together was present in the urine of cases in the RF (all) group compared to the group without renal failure." (PMID 25160665, 2014).